S1PR2 (sphingosine-1-phosphate receptor 2)
Diseases named in the same sentence as S1PR2 in open-access papers (continued):
Sharing a sentence is not in itself a finding about the gene and the disease.
pulmonary fibrosis (18 papers, 2014 to 2025). Chronic progressive interstitial lung disorder characterized by the replacement of the lung tissue by connective tissue, leading to progressive dyspnea, respiratory failure, or right heart failure. "In a bleomycin-induced lung fibrosis animal study, S1PR2 deficiency reduced the total number of cells and the number of macrophages in the bronchoalveolar lavage fluid." (PMID 33922596, 2021). "Inhibition of S1PR2 with antagonists mitigated bleomycin-induced pulmonary fibrosis, reducing collagen deposition, inflammatory cell recruitment, and expression of pro-inflammatory mediators, including IL-4, IL-5, IFN-Y, and TNF-α." (PMID 41511294, 2025). "Genetic deletion of S1pr2 attenuated pulmonary fibrosis, reducing PDGFRα positive fibroblast expansion and decreasing fibronectin and collagen 1a1 mRNA expression compared to wild type controls." (PMID 41511294, 2025). "In this study, we investigated the potential ameliorative effect of JTE-013, a receptor inhibitor of S1PR2, on pulmonary fibrosis." (PMID 37895915, 2023). "S1PR2-aAb and S1PR3-aAb showed a particular association with both PAH and lung fibrosis, in line with their established local biochemical function." (PMID 35860272, 2022). "SphK1 deletion and S1PR2 deletion in lung fibroblasts have both been shown to be protective against bleomycin-induced pulmonary fibrosis in mice." (PMID 34690821, 2021). "In a bleomycin-induced lung fibrosis animal study, genetic deletion of S1PR2 in mice displayed attenuated lung fibrosis compared with wild type mice." (PMID 33922596, 2021). "Pharmacological inhibition of S1PR2 by a S1PR2 antagonist, S1PR2i, inhibited lung fibrosis induced by bleomycin." (PMID 33922596, 2021). "A similar role for S1pr2 in the development of bleomycin-induced lung fibrosis was demonstrated using S1pr2 KO mice and JTE-013, a pharmacological inhibitor of S1PR2 in mice." (PMID 32549377, 2020). "H19 deficiency ameliorated bleomycin-induced pulmonary fibrosis and repressed the activation of TGF-β/Smad and S1pr2/Sphk2 in the lungs of bleomycin-treated mice." (PMID 33138822, 2020). "Fourth, pharmacological blockade of S1PR2 alleviated bleomycin–induced lung fibrosis, suggesting that S1PR2 is a new promising target for treating lung fibrosis." (PMID 29782549, 2018). "Bleomycin–administered S1pr2-/- mice displayed attenuation of lung fibrosis compared with wild-type mice, as evaluated with collagen staining." (PMID 29782549, 2018). "Bone marrow chimera experiments suggested that S1PR2 in bone marrow–derived cells contributes to the development of lung fibrosis." (PMID 29782549, 2018). "The present study first provides evidence for the involvement of S1PR2 in bleomycin–induced lung fibrosis." (PMID 29782549, 2018). "In this point, it is notable that the major site of S1PR2 action in lung fibrosis is likely BM–derived cells." (PMID 29782549, 2018). "We found that genetic deletion of S1pr2 dramatically inhibited bleomycin–induced lung fibrosis through the mechanisms involving the potentiation of the responses to the profibrotic cytokine IL-13." (PMID 29782549, 2018). "Among the cytokines and chemokines that were upregulated by bleomycin administration and suppressed by S1pr2 deletion, IL-13 has recently emerged as a profibrotic mediator in lung fibrosis." (PMID 29782549, 2018). "Second, among several different lung cell types including macrophages, vascular endothelium and fibroblasts that express S1PR2, our studies suggest that S1PR2 in BM–derived cells, most likely in macrophages, contributes to lung fibrosis." (PMID 29782549, 2018). "We show here that genetic deletion of S1pr2 strikingly attenuated lung fibrosis induced by repeated injections of bleomycin in mice." (PMID 29782549, 2018). "Sphingosine-1-phosphate and its receptor S1pr2 have been shown to promote lung fibrosis." (PMID 33138822, 2020). "Hence, we focused on S1PR2 in this study that aimed at revealing a role of S1P signaling in lung fibrosis." (PMID 29782549, 2018).
pulmonary fibrosis (continued). "Thus, S1PR2 facilitates lung fibrosis through the mechanisms involving augmentation of IL-13 expression and its signaling in BALF cells, and represents a novel target for treating lung fibrosis." (PMID 29782549, 2018). "In summary, our study demonstrates a novel role for S1PR2 in regulating cellular phenotypes of BM–derived cells, particularly macrophage, and resultantly fibrogenesis during the development of bleomycin–induced pulmonary fibrosis." (PMID 29782549, 2018). "Finally, pharmacological S1PR2 blockade in S1pr2+/+ mice alleviated bleomycin–induced lung fibrosis." (PMID 29782549, 2018). "S1pr2+/+ and S1pr2-/- littermates were subjected to repeated i.p. injections of bleomycin, which mimics chemotherapeutic regimen in human patients and induces sustained lung fibrosis." (PMID 29782549, 2018). "We studied the effects of pharmacological blockade of S1PR2 on bleomycin–induced lung fibrosis." (PMID 29782549, 2018). "The pathogenic role of the lysophospholipid mediator sphingosine-1-phosphate and its receptor S1PR2 in lung fibrosis is unknown." (PMID 29782549, 2018). "Therefore, S1PR2 may improve pulmonary fibrosis and be involved in the mitochondrial biological processes by regulating YAP." (PMID 37895915, 2023). "In 2018, news studies showed that S1PR2 might also affect pulmonary fibrosis on a transcriptional level; S1PR2 deletion reduced the expression of profibrotic cytokines such as IL-13 and IL-4 in bleomycin-induced pulmonary fibrosis." (PMID 37371823, 2023). "Furthermore, JTE-013, an S1PR2 antagonist, reduced bleomycin-induced pulmonary fibrosis." (PMID 34690821, 2021). "Because IL-13 protein levels were similar in BALFs of wild-type and S1pr2-/- mice, these observations suggest that S1PR2 may be involved in lung fibrosis mainly through potentiating cellular responses to the key profibrotic mediator IL-13 rather than stimulating the production of IL-13 in lung." (PMID 29782549, 2018). "H19 knockout ameliorated bleomycin-induced pulmonary fibrosis through attenuating the TGF-β/Smad and S1pr2/Sphk2 pathways." (PMID 33138822, 2020). "We thus propose that H19 contribute to lung fibrosis of IPF may via regulating both TGF-β/smad and S1pr2/SphK2 signalling." (PMID 33138822, 2020). "In any event, these observations collectively suggest that S1pr2 deletion in BALF cells impedes STAT6 activation and thereby inhibits the expression of STAT6–targeted profibrotic genes including Fizz1, leading to the attenuation of lung fibrosis." (PMID 29782549, 2018). "Here, we describe for the first time the prevalence of S1PR-aAb including the first identification of S1PR2- and S1PR3-aAb in a large cohort of patients and healthy individuals, and report their potential use as both biomarkers and potential therapeutic targets in SSc, PAH, and/or lung fibrosis." (PMID 35860272, 2022). "The increased prevalence of S1PR2- and S1PR3- but not S1PR1-specific aAb in SSc-PAH patients may thus point towards an autoimmune-supported pathomechanism that could contribute to elevated pulmonary vascular resistance and the development of lung fibrosis in SSc-associated PAH." (PMID 35860272, 2022).
hepatocellular carcinoma (17 papers, 2018 to 2026). A malignant tumor that arises from hepatocytes. "The association of conjugated bile acids (CBAs) and S1PR2 alterations with the onset of NASH hepatocarcinogenesis was found in human NAFLD/NASH-HCCs in vivo and in Huh 7 and HepG2 hepatoma cell lines." (PMID 37760534, 2023). "More recently, S1PR2 was reported to contribute to the growth of hepatocellular carcinoma through the AKT pathway." (PMID 35372340, 2022). "In hepatoma cells, the S1P/S1PR2/YAP1 signaling axis stimulates cell proliferation by upregulating connective tissue growth factor." (PMID 36498853, 2022). "Recently S1PR2 has been involved in the growth of hepatocellular carcinoma cells through the activation of PI3K/AKT signaling." (PMID 33225975, 2020). "However, this study along with several recent papers showed that FTY720P can activate S1PR2 in many cell types, like myofibrobalsts, lung fibroblasts, and hepatocellular carcinoma cells." (PMID 40857274, 2025). "It has been shown in some studies that the S1PR2/S1PR3 axis regulated Na+/K+ ATPase in the hepatocellular carcinoma cell line, while others have indicated that Na+/K+ ATPase might serve as an alternative for V-ATPase in astrocytes." (PMID 36719377, 2023). "TCA induces S1pr2 expression and reduces RhoA and ROCK1 levels via S1pr2 in HepG2-NIAS cells (human hepatoma cell line)." (PMID 40507815, 2025).
cholestasis (15 papers, 2017 to 2025). Impairment of the bile flow caused by obstruction within the liver, or outside the liver in the bile duct system. "In cholestatic mice, S1PR2 expression was increased, and S1PR2 deficiency attenuated cholestasis-mediated cholangiocyte proliferation, cholestatic injury, inflammation and fibrosis." (PMID 36899928, 2023). "Our previous studies also reported that S1PR2 deficiency significantly reduced cholestasis-induced cholangiocyte proliferation and liver injury." (PMID 36224648, 2022). "Similarly, macrophage-specific knockdown of S1PR2 reduced cholestasis-associated inflammation and fibrosis by attenuating the chronic-liver-injury-associated NOD-like receptor family pyrin domain containing 3 inflammasome." (PMID 36899928, 2023). "Impaired bile formation and flow (cholestasis) has been associated with increased SphK2/S1P/S1PR2 activation and blocking this pathway with the specific S1PR2 inhibitor, JTE-013, reduced cholestatic liver injury through reduction of total bile acid levels in serum." (PMID 28869494, 2017). "In the context of cholestasis, it has been shown that taurocholic acid spurs HSCs activation through the S1PR2/p38MAPK/YAP signaling pathway." (PMID 40761743, 2025). "We developed a novel model to study the reactive cholangiocyte state in response to pathological stimuli in cholestasis and demonstrated a contributory role of S1PR2 signaling in both injury and NorUDCA/UDCA treatments." (PMID 38407207, 2024). "We previously revealed that S1PR2 promotes an inflammatory response and participates in the progression of cholestasis-induced liver injury." (PMID 36229875, 2022). "Our previous study further indicated that in cholestasis-induced liver injury, S1PR2 promotes an inflammatory response and participates in disease progression." (PMID 36229875, 2022). "In particular, CBAs-induced activation of S1PR2-mediated cholestasis liver injury in mice and invasive growth of human CCA cells by ERK1/2 and AKT Signaling pathway." (PMID 36339341, 2022). "The S1PR2 antagonist, JTE-013, also showed protective effect against BDL-induced cholangiocyte proliferation, suggesting that S1PR2 plays a crucial role in bile acid-induced cholestasis." (PMID 34440841, 2021). "This study did not evaluate changes in ductular reaction or cholangiocyte biology; however, other work has indicated that S1PR2 signaling promotes bile acid-induced cholangiocyte proliferation and cholestasis." (PMID 34440841, 2021). "Our findings indicate that supraphysiological bile acid levels as observed in cholestasis stimulate steroidogenesis via an S1PR2‐ERK‐SF‐1 signalling pathway." (PMID 30664326, 2019). "S1PR2 is also upregulated in livers of patients with cholestasis." (PMID 38407207, 2024). "Furthermore, the S1P/S1PR2 signaling axis has been identified as playing a role in various hepatic processes, including liver injury, fibrosis, and cholestasis." (PMID 38250717, 2024). "As cholestasis-induced liver injury primarily results from inflammation rather than the toxic effects of bile acids, the S1PR2-mediated signaling pathway may link inflammation to cholangiocyte damage in VBDS." (PMID 39854311, 2025).
glioma (12 papers, 2006 to 2024). A benign or malignant brain and spinal cord tumor that arises from glial cells (astrocytes, oligodendrocytes, ependymal cells). "In C6 rat glioma cells, activation of S1PR2 led to downstream signaling via the PLC-Ca2+ system, as well as PLD." (PMID 32977496, 2020). "A PI3K/AKT-dependent increase in invasion of glioma cells was also seen after the stimulation of S1PR2 in a study carried out by Young and Van Brocklyn." (PMID 29149079, 2017). "In contrast, S1PR2, coupled more strongly to G12/13, is known to inhibit migration in other cell types, like vascular smooth muscle cells and glioma cells." (PMID 25147438, 2014). "Moreover, glioma cell invasion in the presence of Nogo-A-Δ20 was regulated by the activity of S1PR2 and IRE1α." (PMID 31062076, 2019). "In addition, S1PR2 was reported to decrease glioma cell motility but enhance invasion through inducing cell interaction with the extracellular matrix and matrix degradation in glioma cell." (PMID 25147438, 2014). "Notably, only S1PR1 and S1PR2 were expressed on C6 glioma cells, which is not consistent with the reported expression in glioma patient samples." (PMID 32977496, 2020).
Sepsis (12 papers, 2015 to 2025). Sepsis is defined as life-threatening organ dysfunction caused by a dysregulated host response to infection. "While S1PR2 signaling was implicated in caspase-11–dependent macrophage pyroptosis in one sepsis model, others found CC1 regulated LPS-driven NLRP inflammasome and caspase-1 activation." (PMID 36719377, 2023). "Sepsis is also associated with increased S1PR2, whereby S1PR2 positivity is associated with increased severity of sepsis, and deficiency of S1PR2 in a sepsis mouse model improved bacterial clearance and survival." (PMID 33003377, 2020). "Furthermore, S1PR2 deficiency/S1PR2 inhibition decreased macrophage pyroptosis and improved survival in E. coli sepsis, posing this receptor as a promising therapeutic approach during sepsis." (PMID 31379883, 2019). "Recent studies identify S1PR2 as a key mediator of sepsis-induced lung injury, particularly through its effects on vascular integrity and inflammatory signaling." (PMID 41511294, 2025). "As for S1PR2, it has been reported to suppress phagocytosis, promote macrophage pyroptosis, and impair antimicrobial defense in the pathogenesis of sepsis." (PMID 39287458, 2024). "It was also proposed that S1PR2 impaired phagocytosis and antimicrobial defense in the pathogenesis of sepsis." (PMID 31379883, 2019). "Another cellular messenger, S1PR2, is the most important receptor for S1P in macrophages and was positively correlated with the severity of sepsis." (PMID 29100348, 2017). "Our recent work has identified endothelial S1PR2 as a robust mediator of vascular permeability and acute vascular injury in several organs in sepsis models." (PMID 26243335, 2015). "While S1PR2 is largely implicated in barrier disruption and inflammatory injury during sepsis-induced ARDS, its functions are not exclusively pathogenic." (PMID 41511294, 2025). "Beyond an impact in the endothelium, S1PR2 also amplifies inflammatory signaling in sepsis." (PMID 41511294, 2025). "Foxo3a is correlated with the dysregulation of glucose homeostasis in the pathogenesis of AOSC-induced sepsis by inhibiting the activation of PI3K/Akt-S1PR2 and NF-κB pathways, hinting at a switched role and therapeutic potentialities in the early stage of sepsis." (PMID 29100348, 2017). "In conclusion, Foxo3a was correlated with the dysregulation of glucose homeostasis in the pathogenesis of AOSC-induced sepsis by inhibiting activation of the PI3K/Akt-S1PR2 and NF-κB pathways, hinting at a switched role and therapeutic potentiality in the early stage of sepsis." (PMID 29100348, 2017). "Thus, this study is the first time to report that Foxo3a is a negative regulator of S1PR2 for inspiring AOSC-induced sepsis." (PMID 29100348, 2017). "Genetic deletion of S1PR2 or pharmacological inhibition of S1PR2 by JTE013 in mice reduced bacterial burden and improved survival rate in mice with sepsis by enhancing bacterial phagocytosis." (PMID 33922596, 2021).
cholangiocarcinoma (11 papers, 2018 to 2025). A carcinoma that arises from the intrahepatic biliary tree (intrahepatic cholangiocarcinoma) or from the junction, or adjacent to the junction, of the right and left hepatic ducts (hilar cholangiocarcinoma). "Additionally, the invasive growth of human cholangiocarcinoma cells induced by taurocholic acid is associated with S1PR2-mediated upregulation of cyclooxygenase-2 expression and prostaglandin E2 production." (PMID 41408647, 2025). "We also reported that conjugated bile acid-induced activation of S1PR2 promoted the growth of cholangiocarcinoma cells and esophageal adenocarcinoma cells." (PMID 40057751, 2025). "Previous studies have demonstrated that bile acids can promote the invasive growth of cholangiocarcinoma cells via S1PR2, which is highly expressed in rat and human cholangiocarcinoma cells and tissues." (PMID 40028184, 2025). "They revealed that conjugated bile acids can promote the aggressive growth of cholangiocarcinoma cells through S1PR2 signaling." (PMID 37894256, 2023). "A recent study has shown that S1PR2 expression is elevated in BECs, and S1PR2 is activated by conjugated bile acid, inducing BECs proliferation, promoting cholangiocarcinoma cell invasive growth." (PMID 36339341, 2022). "This is reminiscence of several previous reports that s1pr2 is highly expressed in cholangiocarcinoma and bile duct cell diseases." (PMID 33446803, 2021). "Thus, in view of high s1pr2 expression in cholangiocytes and its correlation with cholangiocarcinoma and cholestatic liver disease, we chose s1pr2 as a promising candidate receptor to study its role during HCC progression in our zebrafish model." (PMID 33446803, 2021). "Previous studies reported that S1PR2 was the predominant S1PR in hepatocytes and cholangiocarcinoma (CCA) cells (HuCCT1, CCLP1 cell line), and could be activated by S1P." (PMID 36339341, 2022).